IL6 (interleukin 6)
Diseases named in the same sentence as IL6 in open-access papers (continued):
Sharing a sentence is not in itself a finding about the gene and the disease.
COVID-19 (continued). "While IL-6 and ferritin are proposed markers for COVID-19, they did not correlate with the plasma IGFBP-2 levels in our COVID-19 subgroup." (PMID 38137505, 2023). "At the time of hospital admission, the severe/critical COVID-19 patients had significantly higher levels of IL-6 (median, 11.7 pg/mL, IQR 3.5-49.4 pg/mL) than non-severe COVID-19 patients (2.1 pg/mL, IQR 0.5-12.8 pg/mL, p <0.05)." (PMID 36810114, 2023). "While the levels of pro-inflammatory markers, such as CRP, IL-6, IL-1Ra, and TNF-α, were slightly higher, and anti-inflammatory cytokines, such as TGF-β1, were lower in COVID-19/PLWH than in those without HIV, none of these differences was significant." (PMID 37646024, 2023). "Biomarkers that are associated with predicting clinical progression and outcome in COVID-19, such as D-dimers, CRP, and IL-6, were not included in the study." (PMID 37400927, 2023). "We observed that IL-6 and SAA levels were significantly increased in COVID-19 patients and CKD patients without COVID-19 when compared with healthy volunteers." (PMID 38203482, 2023). "In non-COVID-19, DPP3 was significantly correlated with CRP (ρ = 0.35, p < 0.05), as opposed to IL-6 and leucocytes (each p = n.s)." (PMID 37733154, 2023). "The time from SARS-CoV-2 infection’s onset to hospital admission does not seem to influence the prognostic value of CRP, IL-6, and NLR in non-severe COVID-19." (PMID 36831898, 2023). "In COVID-19 patients, those who had AKI had significantly higher IL-6 levels compared with those who did not have AKI (20.4 vs. 5.53 pg/mL), whereas we had the same trend for SAA (300.0 vs. 77.40 μg/L)." (PMID 38203482, 2023). "We determined that increased interleukin (IL)-6 and IL-10, and tumor necrosis factor-α and interferon gamma were not predictive of severe ANE and mortality in children with COVID-19 in this study." (PMID 37602239, 2023). "DPP3 was significantly increased in COVID-19 patients compared to those without SARS-CoV-2 (p < 0.001), opposite to IL-6 and CRP (each p = n.s.)." (PMID 37733154, 2023). "Our research showed that non-surviving hospitalized COVID-19 patients had significantly higher PCT, CRP, LDH and IL-6 levels, which are indicators of both in-hospital mortality and inflammation." (PMID 36836679, 2023). "Our study suggests that IL6 and IL8 levels must be considered for molecular stratification of COVID-19 patients, irrespective of their clinical stratification to pre-empt “cytokine storm”-dependent disease progression." (PMID 36518355, 2022). "Mostly, markers of inflammation such as IL-6, IL-10, CXCL10 (also known as IP10), CXCL11, CCL2, CCL7, CCL8, PD-L1, and IL-18R1 were increased at the early stage of COVID-19 in ICU patients compared to non-ICU ones." (PMID 35269564, 2022). "In this review, we discussed the lncRNA expression profiles in both non-severe and severe COVID-19 cases, as well as the involvement of lncRNAs in lymphopenia, neutrophilia, NLRP3 activation, IL-6 dysregulation, and IFN-I response delay." (PMID 36052163, 2022). "Although a recent study found similar levels of IL6 (and Pentraxin-3) in the BAL fluid of COVID-19 patients irrespective of CAPA." (PMID 36531987, 2022). "Significantly higher levels of IL-6, IL-8, and TNF-α in COVID-19 without HIV vs. HIV/COVID-19 patients (p < 0.05) were observed." (PMID 35891555, 2022). "A retrospective cohort study of 2052 hospitalized patients with COVID-19 showed that inflammatory factors (highly sensitive CRP, procalcitonin) and cytokines (IL-2R, IL-6, IL-8) were higher in cancer patients compared with noncancer patients." (PMID 36033814, 2022). "Cytokines IL-6 and IL1RA have also been shown to be uniquely elevated in response to COVID-19 in comparison to SARS-CoV-2 negative controls." (PMID 34050887, 2022). "Specifically, high plasma levels of IFN-λ1, IFN-γ, IL-1RA, IL-6, MCP-2, and lower levels of Eotaxin-3, IL-12p70, IL-13, MCP-4, MDC, TARC, were observed both in SOT and Non-SOT COVID-19 patients as compared to HCs." (PMID 35075453, 2022).
COVID-19 (continued). "The mean levels of pGSN/IL-6, pGSN/M-CSF, pGSN/HGF, pGSN/IP-10 and pGSN/CTAK were determined and compared between COVID-19 patients and COVID-19 negative controls." (PMID 36148234, 2022). "At the time of SARS-CoV2 diagnosis, COVID-19 non-survivors had significantly higher CRP, IL-6, D-Dimer, and antithrombin levels compared to the survivors." (PMID 35883726, 2022). "COVID-19 ICU patients had significantly higher levels of the proinflammatory cytokines CXCL1, IL-1β, IL-6, MCP-1, and TNF-α compared to the non-COVID group." (PMID 35502320, 2022). "In Non-SOT COVID-19 patients, we observed 6 (IL-13, IL-10, IFN-γ, IL-12p70, MCP-2, IL-6) and 9 (IL-16, IL-13, TNF-α, IL-6, IL-18, IL-15, MIP-1α, IL-2Ra, IL-8) cytokine correlations with monocyte and neutrophil derived cfDNA, respectively." (PMID 35075453, 2022). "Serum levels of IP-10 and MCP-1 are elevated in critically ill COVID-19 patients, but MIP-1α and IL-6 are not increased proportionately." (PMID 35822078, 2022). "Consistently, cytokine profiles from both severe COVID-19 patients and SARS-CoV-2 infected lung epithelial cells were enriched for pro-inflammatory cytokines, specifically IL-6, and lacked type I/III IFNs." (PMID 35022513, 2022). "We have identified 11 cytokine/chemokine differences in both SOT and Non-SOT COVID-19 patients as compared to healthy controls, including cytokines with higher (IFN-λ1, MCP-2, IL-6, IL-1RA, IFN-γ) or lower (Eotaxin-3, MDC, TARC, IL-13, MCP-4, IL-12p70) levels." (PMID 35075453, 2022). "The NP levels were significantly higher in the COVID-19 patients than in the non-COVID-19 patients, while biopterin, CRP and IL-6 were not changed significantly." (PMID 35529699, 2022). "We observed significantly increased levels of inflammatory cytokines/chemokines such as GM-CSF, IL-15, IL-6 and IL-8 in both SOT and Non-SOT COVID-19 patients who subsquently developed severe disease compared to patients with mild/moderate disease." (PMID 35075453, 2022). "Tocilizumab is a potent inhibitor of IL-8 and IL-6 and inhibits angiogenesis, however to what extent it inhibits EGF in COVID-19 is not known." (PMID 35930528, 2022). "Studies have reported that the levels of cytokines (IL-6, IL-2R, and IFN-γ) in cancer patients with COVID-19 are significantly higher than those in noncancer patients." (PMID 36033814, 2022). "In particular, IL-6 and IL-8 were expressed significantly less in HIV/COVID-19 patients than in COVID-19 patients without HIV, suggesting a possible impact of immunosuppression on dampening the inflammatory response." (PMID 35891555, 2022). "Since serum CRP and IL-6 are natively elevated in NAFLD patients, increased levels in COVID-19 are not an unexpected finding." (PMID 35743825, 2022). "Finally, although not yet approved for the treatment of patients with severe COVID-19 in alternative to anti-IL-6 agents, future research could assess the potential role of monoclonal antibodies targeting IL-1 (anakinra and canakinumab) in patients with cytokine storm and high risk of CAPA." (PMID 35741174, 2022). "Here, we show that human monocytes exposed to IC of SARS CoV-2 pseudovirus with plasma from COVID-19 patients but not from healthy subjects, produce PGE2 and IL-6, IL-8, and IL-1β cytokines only in the presence of soluble DD." (PMID 35385545, 2022). "In the study, the results showed that the levels of pro-inflammatory cytokines (IL-2, IL-4, IL-6, TNF-α, and IFN-γ) were not different between mild, moderate, and severe/critical groups of children with COVID-19." (PMID 36294306, 2022). "Regarding the interleukins, gene expression of IL6, but not IL7, was increased in PBCs of COVID-19 patients (by 89%) as compared to control subjects (Student’s t test)." (PMID 36009555, 2022).
COVID-19 (continued). "MSCs were used in several pilot studies for treatment of severe COVID-19, demonstrating their efficiency by patient clinical improvement, better oxygenation and decreased inflammatory markers (CRP, IL-6, TNF-α, procalcitonin) with no observed adverse effects." (PMID 36499448, 2022). "However, as the IL-6 levels of the patients in the present study were not significantly high, even in the severe group, it could be concluded that IL-6 inhibitors may not be effective against COVID-19." (PMID 36282812, 2022). "We found that CRP correlated with IL-6 in either COVID-19 or non-COVID-19 patients (rs = 0.65, p < 0.001 and rs = 0.72, p < 0.001, respectively), and that NP correlated with CRP in non-COVID-19 patients (rs = 0.618, p = 0.00217)." (PMID 35529699, 2022). "Meanwhile, we did not observe any significant difference in the IL-6 levels between the WT and Δ382 infected patients, suggesting differential roles of ORF8 in inducing hyperinflammation in COVID-19." (PMID 34716845, 2022). "Significant levels of the inflammatory cytokines IL-6, IL-8, IL-10, and TNF-α have been documented in severe COVID-19 compared with non-severe disease cases, reflecting this phenomenon." (PMID 36556051, 2022). "Elevated sera cardiac troponins, IL-6, creatine kinase, D-dimer and Ig FLC biomarkers indicate cardiac damage and inflammation characteristic of myocarditis, especially in the COVID-19 patients without a history of CVD that are under 50 years of age." (PMID 36292038, 2022). "pGSN alone outperformed cytokines (IL-6, IP-10, HGF and M-CSF) in discriminating COVID-19+ patients from non-COVID-19 suggesting that pGSN is a potential biomarker indicative of COVID-19 infection." (PMID 36148234, 2022). "Systems biology studies have shown that proinflammatory cytokines, IL-6, IL-1β, and TNF-α, originating from SARS-CoV-2 infected lungs, but not from the peripheral blood cells, contribute to COVID-19 severity." (PMID 36298628, 2022). "In addition, our observations suggest that IL-6 is probably not the only driving pathway of severe COVID-19 and that molecules upstream of IL-6 in the inflammatory cascade, such as IL-1, might represent more suitable targets to quench Sars-CoV-2 induced hyper-inflammation." (PMID 33995419, 2021). "We detected increases in IL-18, IL-6, and MIP-1α in the COVID-19 ICU group versus controls and the non-ICU group (FDR < 0.05)." (PMID 34960684, 2021). "Significantly elevated levels of the inflammatory cytokines TNF-α, IL-1, IL-6, IFN-λ3, IL-6, IP-10, and CXCL9 have been documented in severe COVID-19 compared to non-severe disease cases." (PMID 34399775, 2021). "Compared to COVID − 19 patients without headache, serum levels of HMGB1, NLRP3, IL-6, angiotensin II, and ACE2 were significantly higher in COVID-19 patients with severe headache." (PMID 34384355, 2021). "When comparing biomarkers between COVID-19 patients who developed ARDS to those not requiring ICU treatment, progranulin and interleukin-6 were the only biomarkers to differ significantly (p < 0.001) on the day of admission to the hospital." (PMID 34476621, 2021). "We found that the serum levels of multiple pro-inflammatory cytokines or biomarkers, including IL-6, IL-10, IL-8, TNF-α, IL-1β, IL-2R, ferritin, hs-CRP and procalcitonin were substantially elevated in non-survivors with COVID-19." (PMID 34521370, 2021). "Compared with that in the non-COVID-19 group, the levels of Interleukin-2 (IL-2), Interleukin-6 (IL-6), Interferon-gamma (IFN-γ) and tumor necrosis factor-alpha (TNF-α) were significantly increased in the COVID-19 group (P < 0.05)." (PMID 35071136, 2021). "Previous results from our group have shown that circulating IL-6 and IL-10 were lower, while TNF-α and IL-8 levels were higher, in the same critically ill COVID-19 patients compared to the critically ill non-COVID-19 patients." (PMID 34575667, 2021).
COVID-19 (continued). "Interestingly, the secretion of IL-6, IL-8, TNF-α, IFN-γ and IL-10 was significantly elevated in CARγ and CARζ cells treated with SARS-CoV-2 virions, suggesting that these CAR macrophages may not be suitable for application in severe patients or patients with late-stage COVID-19." (PMID 34367135, 2021). "Among the inflammatory parameters, our systematic review and analysis demonstrated a marked elevation in the level of circulating IL-6 and TNF in severe COVID-19 and MERS patients in comparison to non-severe groups." (PMID 34046036, 2021). "Compared to nondiabetic COVID-19 patients, diabetic COVID-19 patients are characterized by a higher percentage of CD4+ T cell and a lower percentage of CD8+ T cells and higher serum levels of IL-6, IL-2, IL-10, and INFγ." (PMID 34157054, 2021). "According to our findings, MHD patients with COVID-19 who experienced non-surviving outcome had more elevated CRP, IL6 and procalcitonin as well as fibrinogen levels at various points compared to survivors." (PMID 33967613, 2021). "In contrast, the serum levels of IL-4, IL-6, IL-10, interferon-γ, and TNF-α were lowest in infected HD patients compared to non-infected HD patients or COVID-19-infected patients with normal renal function." (PMID 33466527, 2021). "We found that eight pro-inflammatory factors (IL-6, IL-8, IL-13, IL-1ra, MIP-1a, IP-10) out of 27 analyzed serum cytokines were modulated in COVID-19 patients irrespective of cancer status." (PMID 34716309, 2021). "Active AOSD patients also had significantly higher levels of IL-6 and TNF-α than non-severe COVID-19 patients." (PMID 34367188, 2021). "With that, the comparison of blood levels of IL-1, IL-1RA, IL-6, IL-8, IL-18, and TNF-a in ARDS COVID-19 and bacterial sepsis revealed no significant changes." (PMID 34299201, 2021). "In conclusion, we showed an increase in the serum levels of cytokines, including IL1-β, IL-6, IL-8, and TNF-α in ICU patients relative to mild COVID-19, while RANTES serum levels were increased in the mild, not ICU patients." (PMID 34276659, 2021). "IL-6 and IL-18, among others, were elevated in ICU status COVID-19 patients versus non-ICU COVID-19 patients and hospitalized controls." (PMID 34960684, 2021). "Proinflammatory molecules, such as IL-2, IL-4, IL-5, IL-6, IL-10, IL-13, TNF-α, IFN-Υ, and CRP, were found at higher levels in COVID-19 patients with DM than in COVID-19 patients without DM." (PMID 34786431, 2021). "We found that for IL-6 and CRP showed a similar pattern as H3.1 nucleosomes in which there was a statistically significant difference in COVID-19 patients in ICU compared to the in outpatient/ER but not in the regular hospital ward." (PMID 33816549, 2021). "IL6 mRNA and protein expression did not correlate with CHRFAM7A mRNA expression in both COVID-19 and HC (data not shown)." (PMID 34088975, 2021). "Unlike increased levels of TNFα, IL-6, IL-8, IL-10, CXCL8, and IP-10 observed in H1N1 infected pregnant patients, COVID-19 pregnant patients showed relatively lower expressions of pro-inflammatory and anti-inflammatory cytokines." (PMID 34012458, 2021). "Extensive serum (not plasma) proteomic analysis of COVID-19 patients pointed to the possibility of decrease in FXIII-B in the sera of COVID-19 patients, in a correlation to increase in IL-6 levels." (PMID 34736472, 2021). "As shown by a study on 452 patients, markedly elevated levels of IL-6 and slightly enhanced levels of TNF and IL-2R, while no marked change of IL-1β, were observed in COVID-19 patients." (PMID 33907514, 2021). "Surprisingly, we observed a trend toward lower ELF concentrations of IL-6 in COVID-19 patients compared with non-COVID-19 ARDS patients (p = 0.11), thus challenging the interest of anti-IL-6 therapies in severe COVID-19 pneumonia." (PMID 33138839, 2020).
COVID-19 (continued). "COVID-19 patients considered by the physician as “not severely inflamed” and who therefore did not undergo EBP had lower levels of IL-6 and SOFA score than those undergoing EBP with the oXiris membrane." (PMID 33046113, 2020). "Up-regulation of IL-6, G-CSF, IL-1RA, and MCP1 predicted death in patients with COVID-19 but were not statistically higher than patients with influenza." (PMID 33187979, 2020). "In a retrospective study of 77 COVID-19 patients, treatment with IFN-α2b with or without arbidol substantially reduced the duration of viral shedding and inflammatory markers, including IL-6 and CRP." (PMID 33584679, 2020). "After seven days of treatment (T1), COVID-19 patients belonging to group A (not receiving canrenone) showed a significant improvement in [K+]plasma (4.6 mmol/L, p < 0.001), CRP (2.2 mg/dL), IL-6 (13 pg/mL), and ΔA-aO2 (135 mmHg)." (PMID 32933039, 2020). "Unlike the proinflammatory cytokine IL-6, the anti-inflammatory Th2 cytokine TGF-β is not overproduced in COVID-19 patients." (PMID 32758273, 2020). "Similar to these findings, in a small trial CB Tregs were given to two COVID-19 patients with ARDS, resulting in a significant reduction of inflammatory markers including IL-6, IL-12, TNF-α, IFN-γ and MCP-1, without adverse reactions." (PMID 33302366, 2020). "Moreover, due to the absence of data, our study did not consider or analyze the baseline levels of IL-6; therefore, we could not illustrate the specific function of IL-6/IL-6R/JAK pathway antibodies on patients with COVID-19 with different baseline IL-6 levels." (PMID 33384605, 2020). "The lack of GC responses in COVID-19, due to increased TNF and IL-6 expression and the rapid progress of WP disruption, result in loss of hypermutation process, which may impair the production of high-affinity antibodies in patients with severe disease." (PMID 41210940, 2025). "Patients with ILD showed no significant elevation in cytokines (IL-6, TNF-α, and IFN-γ), inflammatory biomarkers, C-reactive protein, ferritin, or D-dimer, indicating that patients with COVID-19 and ILD did not manifest additional hyperinflammation compared with the control individuals." (PMID 40573986, 2025). "Additionally, other important inflammatory markers relevant to severe COVID-19 and coinfections, such as LDH, ferritin, and IL-6, were not measured in this patient." (PMID 41010278, 2025). "The study identified IL-6, TNF, IL-1β, IL-10, and IL-2 as the five most distinctive cytokines that could effectively differentiate between individuals who had COVID-19 (including those with long COVID) and those who had never been exposed to the virus." (PMID 39518964, 2024). "Counts of lymphocytes, neutrophils, platelets, NMR, NLR, D-dimer, interleukin-6, CRP levels, and lactate dehydrogenase (LDH) levels may be able to help differentiate between severe and non-severe COVID-19." (PMID 39723295, 2024). "Similarly, our results showed a significant reduction in IL-6 in COVID-19 patients receiving supplemented O3FA PN, whereas COVID-19 patients receiving regular ILE did not." (PMID 39339646, 2024). "However, the role of the inflammatory pathway in the clinical manifestations in the present study is uncertain, given that the concentrations of inflammatory markers, IL-6 and CRP, were similar in all individuals, irrespective of post-COVID-19 symptoms." (PMID 39056056, 2024). "In this study, it was found that COVID-19 patients with chronic CVD and continued use of statins or RAASI had lower plasma concentrations of IL-6 than COVID-19 patients with no co-morbidities, despite their more advanced age and more prevalent immunosuppressive conditions." (PMID 39518552, 2024). "Similarly, IL-6 and MCP levels were significantly reduced in nonsevere COVID-19 patients, with mean values of 11.87 pg/mL and 240.67 pg/mL, respectively, compared with 30.35 pg/mL and 439.11 pg/mL in severe patients." (PMID 39062105, 2024).